Y_RNA (Y RNA )
Gene: Miscellaneous RNA gene on chromosome 3 (170,244,782 to 170,244,881, forward strand). Ensembl gene ENSG00000200118.
Homologues: Orthologues: chimpanzee Y_RNA (98% identical), macaque Y_RNA (97% identical), guinea pig Y_RNA (96% identical). Paralogues in human: Y_RNA (94% identical), RNY3 (93% identical), Y_RNA (93% identical), Y_RNA (92% identical), Y_RNA (91% identical), RNY3P1 (90% identical), Y_RNA (90% identical), RNY3P16 (89% identical), RNY3P2 (89% identical), Y_RNA (89% identical), RNY3P4 (88% identical), Y_RNA (88% identical), and 97 more.